KBTBD11-OT1 (KBTBD11 overlapping transcript 1 )
Gene: Protein-coding gene on chromosome 8 (1,763,888 to 1,958,627, forward strand). Ensembl gene ENSG00000283239.
Genetic constraint (gnomAD): Missense variants: 324 observed, 281.43 expected, observed/expected ratio (o/e) 1.15, 90% interval 1.05 to 1.26. Synonymous variants: 138 observed, 121.27 expected, observed/expected ratio (o/e) 1.14, 90% interval 0.99 to 1.31.